PTGR2 (prostaglandin reductase 2)
Description:
Functions as 15-oxo-prostaglandin 13-reductase and acts on 15-keto-PGE1, 15-keto-PGE2, 15-keto-PGE1-alpha and 15-keto-PGE2-alpha with highest activity towards 15-keto-PGE2. Overexpression represses transcriptional activity of PPARG and inhibits adipocyte differentiation (By similarity).
Synonyms: ZADH1; FLJ39091; HEL-S-298; PGR2
Tractability: Small molecule: a structure with a bound ligand is known; it has a high-quality binding pocket. PROTAC: ubiquitination databases record sites on it.
Gene: Protein-coding gene on chromosome 14 (73,851,799 to 73,885,726, forward strand). Ensembl gene ENSG00000140043.
Subcellular location: Cytoplasm
Subcellular location (Human Protein Atlas): Vesicles
Pathways (Reactome):
Metabolism: Synthesis of Prostaglandins (PG) and Thromboxanes (TX)
Gene Ontology:
Molecular function: 15-oxoprostaglandin 13-reductase [NAD(P)+] activity; protein binding; zinc ion binding; oxidoreductase activity, acting on the CH-CH group of donors, NAD or NADP as acceptor
Biological process: prostaglandin metabolic process
Cellular component: cytoplasm
Genetic constraint (gnomAD): Loss-of-function variants: 15 observed, 20.63 expected, observed/expected ratio (o/e) 0.73, 90% interval 0.49 to 1.12. The upper end of that interval is the gene's LOEUF score, 1.12, which puts it in group 4 of 6, group 1 being the genes least tolerant of losing a copy. Missense variants: 239 observed, 279.39 expected, observed/expected ratio (o/e) 0.86, 90% interval 0.77 to 0.95. Synonymous variants: 76 observed, 96.46 expected, observed/expected ratio (o/e) 0.79, 90% interval 0.65 to 0.95.
Homologues: Orthologues: chimpanzee PTGR2 (100% identical), macaque PTGR2 (98% identical), pig PTGR2 (92% identical), dog PTGR2 (91% identical), rabbit PTGR2 (91% identical), guinea pig PTGR2 (89% identical), mouse Ptgr2 (86% identical), rat Ptgr2 (84% identical), tropical clawed frog ptgr2 (68% identical), zebrafish ptgr2 (63% identical), Caenorhabditis elegans M106.3 (45% identical). Paralogues in human: PTGR1 (37% identical), PTGR3 (21% identical), TP53I3 (19% identical), VAT1L (18% identical), RTN4IP1 (17% identical), VAT1 (17% identical), CRYZ (17% identical), SORD (16% identical), ADH1B (16% identical), ADH1A (15% identical), ADH1C (15% identical), ADH4 (15% identical), and 5 more.
Diseases named in the same sentence as PTGR2 in open-access papers:
PTGR2 is named in the same sentence as 19 diseases in open-access papers, as found by Europe PMC text mining. Sharing a sentence is not in itself a finding about the gene and the disease. The quoted sentences say what the papers report.
gastric cancer (2 papers, 2016 to 2023). A primary or metastatic malignant neoplasm involving the stomach. "PTGR2-knockdown gastric cancer cells rendered them more sensitive to cisplatin and 5-FU compared with the PTGR2-overexpressing cells." (PMID 38304289, 2023). "The biological functions of PTGR2 we observed in pancreatic cancer cells seemed to be similar to gastric cancer cells." (PMID 26820738, 2016). "Previously, we have reported a novel oncogenic role of PTGR2 in gastric cancer, where PTGR2 was discovered to modulate ROS-mediated cell death and tumor transformation." (PMID 26820738, 2016). "Previously, we also established a novel role of PTGR2 in cancer biology, where PTGR2 takes part in ROS-mediated cell death and tumor transformation in gastric cancer." (PMID 26820738, 2016). "In the present study, we provided evidence showing that the oncogenic property of PTGR2 is not only specific to gastric cancer, but also impact on pancreatic cancers." (PMID 26820738, 2016). "Importantly, tumor-part PTGR2 stain intensity negatively correlated with the survival of patients with intestinal type gastric cancer." (PMID 26820738, 2016). "Although much work is still needed to clarify the underlying specific mechanisms, clinically we also found that majority of pancreatic ductal adenocarcinoma tissues were stained positive for PTGR2 expression, similar to what we observed in human gastric cancer." (PMID 26820738, 2016). "Similar to those observed in gastric cancer cells, annexin V-7AAD binding assay and flow cytometric H2-DCFDA staining further showed that PTGR2-silenced BxPC-3 exerted elevated percentage of both apoptotic and necrotic cells as well as induced ROS production." (PMID 26820738, 2016). "In the present study, we demonstrated that the oncogenic potency of PTGR2 is not restricted to gastric cancer but is also observed in pancreatic cancer." (PMID 26820738, 2016). "Besides our previous finding that PTGR2, an enzyme degrading 15-keto-PGE2, modulates cell death and tumor transformation of gastric cancer cells, recent studies also showed an emerging role of 15-PGDH, an enzyme generating 15-keto-PGE2, as a tumor suppressor in different cancers." (PMID 26820738, 2016). "We found that majority (85.5%) of the pancreatic ductal adenocarcinoma tissues were stained positive for PTGR2 expression but not expressed in the adjacent normal parts, suggesting PTGR2 may play a general oncogenic role not restricted to previously reported gastric cancer." (PMID 26820738, 2016).
pancreatic cancer (2 papers, 2016 to 2023). "Gene silencing of PTGR2 suppressed pancreatic cancer cell growth and induced cancer cell death through increased 15-keto-PGE2 and ROS levels." (PMID 38304289, 2023). "Silencing of PTGR2 suppressed pancreatic cancer cell growth and induced cancer cell death through increased 15-keto-PGE2 and ROS levels." (PMID 26820738, 2016). "In the present study, we demonstrated the oncogenic potency of PTGR2 in pancreatic cancer." (PMID 26820738, 2016). "Our data highlight the therapeutic potential of targeting PTGR2/15-keto-PGE2 for pancreatic cancer." (PMID 26820738, 2016). "In summary, we revealed the importance of PTGR2/15-keto-PGE2 in antioxidative signaling and in tumor cell death involving xCT and CTH in some of the pancreatic cancer cells." (PMID 26820738, 2016). "We next examined the expressions of major enzymes in the prostaglandin E2 pathway, including COX1, COX2, 15-PGDH and PTGR2, as well as the level of 15-keto-PGE2, in different pancreatic cancer cell lines." (PMID 26820738, 2016). "PTGR2 is found to be expressed in pancreatic cancer tissues, but absent in normal pancreatic tissues." (PMID 26820738, 2016). "All five pancreatic cancer cell lines expressed 15-PGDH and PTGR2." (PMID 26820738, 2016). "Not only did in vitro immunoassay show reduced level of PTGR2 product 13,14-dihydro-15-keto-PGE2, LC/MS quantification further confirmed the higher level of 15-keto-PGE2 and reduced level of 13,14-dihydro-15-keto-PGE2 in PTGR2-silenced pancreatic cancer cells as compared to controls." (PMID 26820738, 2016).
Anxiety (1 paper, 2018). Intense feelings of nervousness, tension, or panic often arise in response to interpersonal stresses. "Gene PTGR2 also showed a Bonferroni significant association in the non-functionally annotated category with the diagnosis of ICD-9 code 309.28 (anxiety and depression)." (PMID 29545597, 2018).
colorectal cancer (1 paper, 2023). A primary or metastatic malignant neoplasm that affects the colon or rectum. "Lipid uptake, storage, and metabolism is upregulated in cancer to meet the increased energy demands, The higher PTGR2 expression in FOLFIRI responders might align with the increase metabolism in the colorectal cancer cells making them more susceptible to FOLFIRI." (PMID 38304289, 2023).
coronary heart disease (1 paper, 2024). "TOMM20 levels can signal changes in mitochondrial function relevant to increased risk of coronary heart disease in diabetic patients, and PTGR2 is involved in the metabolism of prostaglandin E2, which is involved in vasoconstriction." (PMID 39796045, 2024).
diabetes (1 paper, 2025). "In conclusion, inhibition of PTGR2 is a new therapeutic approach to treat diabetes and obesity through increasing endogenous PPARγ ligands while avoiding side effects including increased adiposity, fluid retention, and osteoporosis." (PMID 40119175, 2025). "In this study, we sought to inhibit PTGR2 to increase endogenous PPARγ ligands for treating diabetes without relying on synthetic PPARγ ligands." (PMID 40119175, 2025).
gastric tumor (1 paper, 2016). "Previously, we showed clinical significance for the high PTGR2 stain intensity in tumor areas relative to adjacent non-tumor areas in human gastric tumor tissues." (PMID 26820738, 2016).
Glucose intolerance (1 paper, 2018). Glucose intolerance (GI) can be defined as dysglycemia that comprises both prediabetes and diabetes. "In our study, we also identified functionally annotated variants in the PTGR2 gene (from all categories where functionally annotated mutations were tested) with “abnormal glucose intolerance of mother”." (PMID 29545597, 2018).
Hepatic steatosis (1 paper, 2025). Steatosis is a term used to denote lipid accumulation within hepatocytes. "The Hematoxylin-eosin (H&E) stain of the liver showed a lesser degree of hepatic steatosis and the hepatic triglyceride content is lower in Ptgr2−/− mice than in controls." (PMID 40119175, 2025). "Our results highlighted inhibition of PTGR2 as a new effective approach to prevent obesity, improve insulin sensitivity and insulin tolerance, and reduce hepatic steatosis without adverse side effects through increasing endogenous PPARγ ligands." (PMID 40119175, 2025). "Either genetic or pharmacological inhibition of PTGR2 prevented diet-induced obesity, improved insulin sensitivity, glucose tolerance, and ameliorated hepatic steatosis without fluid retention or osteoporosis." (PMID 40119175, 2025). "Either genetic inhibition of PTGR2 or PTGR2 inhibitor BPRPT0245 protected mice from diet-induced obesity, insulin resistance, and hepatic steatosis without causing fluid retention and osteoporosis." (PMID 40119175, 2025). "In conclusion, this study showed that genetic or pharmacological inhibition of PTGR2 prevented diet-induced obesity, reduced insulin resistance, and decreased hepatic steatosis via increasing endogenous PPARγ ligands without adverse side effects such as fluid retention and osteoporosis." (PMID 40119175, 2025).
Obesity (1 paper, 2025). Accumulation of substantial excess body fat. "Increasing 15-keto-PGE2 through either genetic disruption or pharmacological inhibition of its degrading enzyme PTGR2 or direct injection of 15-keto-PGE2 into mice improved insulin sensitivity and prevented diet-induced obesity." (PMID 40119175, 2025). "Direct administration of 15-keto-PGE2, as well as genetic or pharmacological inhibition of PTGR2 (the enzyme responsible for degrading 15-keto-PGE2), prevented diet-induced obesity, improved glucose abnormalities, and reduced fatty liver without causing fluid retention or osteoporosis." (PMID 40119175, 2025).
pancreatic ductal adenocarcinoma (1 paper, 2016). An infiltrating adenocarcinoma that arises from the epithelial cells of the pancreas. "To further dissect the role of PTGR2 in cancer biology, we examined the expression of PTGR2 in pancreatic ductal adenocarcinoma specimens from 76 patients using immunohistochemical staining." (PMID 26820738, 2016). "PTGR2 is strongly stained in human pancreatic ductal adenocarcinoma tissue." (PMID 26820738, 2016). "First, we observed that the majority of the human pancreatic ductal adenocarcinoma tissues was stained positive for PTGR2 expression but not in the adjacent normal parts." (PMID 26820738, 2016).
sarcopenia (1 paper, 2024). Progressive decline in muscle mass due to aging which results in decreased functional capacity of muscles. "The loss of DJ-1 also accelerated molecular features associated with sarcopenia, such as a decrease in the NAD+/NADH ratio and a reduction in Prostaglandin reductase 2 and Cytosolic glycerol-3-phosphate dehydrogenase levels." (PMID 39765837, 2024).
cancer (2 papers, 2016 to 2023). A tumor composed of atypical neoplastic, often pleomorphic cells that invade other tissues. "Together with our clinical finding, the significance of PTGR2 in cancer biology as well as plausible target to improve therapeutic efficacy of existing cancer drugs is worth continuing and exploring." (PMID 26820738, 2016). "Importantly, we showed for the first time that the impact of PTGR2 on cancer cell death seemed to be the resultant of a defective antioxidative defense system involving xCT and CTH, both of which are important regulators of intracellular reduced GSH." (PMID 26820738, 2016).
tumor (2 papers, 2016 to 2025). "Finally, the cellular stress associated protein, prostaglandin reductase 2 (Ptgr2), was completely ablated in the hippocampus of CANTumor versus CANRegress mice, suggesting elevated levels of reactive oxygen species and cell death in the mice that experienced sustained tumour burden." (PMID 40172096, 2025). "We showed both in vitro and in vivo that knockdown of PTGR2 suppressed tumor growth and induced apoptosis through ROS-mediated signaling involving ERK1/2 and caspase 3 activities." (PMID 26820738, 2016). "We further observed strong PTGR2 staining in tumor part relative to adjacent non-tumor areas in gastric tissues." (PMID 26820738, 2016).
neurodegenerative disease (1 paper, 2022). A disorder of the central nervous system characterized by gradual and progressive loss of neural tissue and neurologic function. "Additionally, the neural microenvironment also responds to xenobiotic injuries and neurodegenerative diseases by adopting an inflammatory profile, which can be visualized in the proteomic analysis by the absence of Prostaglandin reductase 2 (Q5BK81) in the exposed group." (PMID 36293377, 2022).
PTGR2 also shares sentences with these, for which no sentence is quoted: depression (1 paper); Insulin resistance (1); osteoporosis (1); pancreatic adenocarcinoma (1).